EIF4A3 (eukaryotic translation initiation factor 4A3)
Description:
ATP-dependent RNA helicase. Involved in pre-mRNA splicing as component of the spliceosome. Core component of the splicing-dependent multiprotein exon junction complex (EJC) deposited at splice junctions on mRNAs. The EJC is a dynamic structure consisting of core proteins and several peripheral nuclear and cytoplasmic associated factors that join the complex only transiently either during EJC assembly or during subsequent mRNA metabolism. The EJC marks the position of the exon-exon junction in the mature mRNA for the gene expression machinery and the core components remain bound to spliced mRNAs throughout all stages of mRNA metabolism thereby influencing downstream processes including nuclear mRNA export, subcellular mRNA localization, translation efficiency and nonsense-mediated mRNA decay (NMD). Its RNA-dependent ATPase and RNA-helicase activities are induced by CASC3, but abolished in presence of the MAGOH-RBM8A heterodimer, thereby trapping the ATP-bound EJC core onto spliced mRNA in a stable conformation. The inhibition of ATPase activity by the MAGOH-RBM8A heterodimer increases the RNA-binding affinity of the EJC. Involved in translational enhancement of spliced mRNAs after formation of the 80S ribosome complex. Binds spliced mRNA in sequence-independent manner, 20-24 nucleotides upstream of mRNA exon-exon junctions. Shows higher affinity for single-stranded RNA in an ATP-bound core EJC complex than after the ATP is hydrolyzed. Involved in the splicing modulation of BCL2L1/Bcl-X (and probably other apoptotic genes); specifically inhibits formation of proapoptotic isoforms such as Bcl-X(S); the function is different from the established EJC assembly. Involved in craniofacial development.
Synonyms: eIF-4A-III; eIF4A-III; DDX48; KIAA0111; EIF4AIII; Fal1; MUK34; NMP265; NUK34; RCPS
Tractability: Small molecule: a structure with a bound ligand is known; a high-quality ligand is known; it has a binding pocket of medium quality. PROTAC: UniProt records ubiquitination sites on it; ubiquitination databases record sites on it; its protein half-life has been measured; a small molecule that binds it is known.
Target class: Enzyme; Hydrolase
Gene: Protein-coding gene on chromosome 17 (80,134,369 to 80,147,151, reverse strand). Ensembl gene ENSG00000141543.
Subcellular location: Nucleus; Nucleus speckle; Cytoplasm
Subcellular location (Human Protein Atlas): Nucleoplasm; Cytosol; Vesicles
Pathways (Reactome):
Metabolism of RNA: Deadenylation of mRNA; Nonsense Mediated Decay (NMD) enhanced by the Exon Junction Complex (EJC); Transport of Mature mRNA derived from an Intron-Containing Transcript; mRNA 3'-end processing; mRNA Splicing - Major Pathway
Developmental Biology: M-decay: degradation of maternal mRNAs by maternally stored factors; Regulation of expression of SLITs and ROBOs; Z-decay: degradation of maternal mRNAs by zygotically expressed factors
Disease: Dengue Virus Genome Translation and Replication; Dengue Virus-Host Interactions
Immune System: ISG15 antiviral mechanism
Gene Ontology:
Molecular function: ATP binding; ATP hydrolysis activity; mRNA binding; poly(A) binding; protein binding; RNA binding; RNA helicase activity; helicase activity; nucleic acid binding; ribonucleoprotein complex binding; RNA stem-loop binding; selenocysteine insertion sequence binding
Biological process: embryonic cranial skeleton morphogenesis; mRNA export from nucleus; mRNA metabolic process; mRNA splicing, via spliceosome; negative regulation of translation; nuclear-transcribed mRNA catabolic process, nonsense-mediated decay; positive regulation of translation; regulation of nuclear-transcribed mRNA catabolic process, nonsense-mediated decay; associative learning; cellular response to brain-derived neurotrophic factor stimulus; cellular response to selenite ion; exploration behavior; negative regulation of excitatory postsynaptic potential; negative regulation of gene expression; negative regulation of selenocysteine incorporation; regulation of translation at postsynapse, modulating synaptic transmission
Cellular component: catalytic step 2 spliceosome; cytoplasm; exon-exon junction complex; membrane; nuclear speck; nucleoplasm; nucleus; post-spliceosomal complex; spliceosomal complex; U2-type catalytic step 1 spliceosome; U2-type catalytic step 2 spliceosome; cytosol; dendrite; glutamatergic synapse; neuronal cell body; postsynapse; ribonucleoprotein complex
Genetic constraint (gnomAD): Loss-of-function variants: 1 observed, 56.65 expected, observed/expected ratio (o/e) 0.0177, 90% interval 0.005 to 0.084. The upper end of that interval is the gene's LOEUF score, 0.084, which puts it in group 1 of 6, group 1 being the genes least tolerant of losing a copy. Missense variants: 220 observed, 557.84 expected, observed/expected ratio (o/e) 0.39, 90% interval 0.35 to 0.44. Synonymous variants: 193 observed, 204.94 expected, observed/expected ratio (o/e) 0.94, 90% interval 0.84 to 1.06.
Homologues: Orthologues: macaque EIF4A3 (100% identical), guinea pig EIF4A3 (99% identical), pig EIF4A3 (99% identical), rat Eif4a3 (99% identical), dog EIF4A3 (99% identical), mouse Eif4a3 (99% identical), mouse Eif4a3l2 (98% identical), mouse Eif4a3l1 (97% identical), chimpanzee EIF4A3 (97% identical), tropical clawed frog eif4a3 (97% identical), zebrafish eif4a3 (95% identical), Drosophila melanogaster CG7483 (85% identical), and 2 more. Paralogues in human: EIF4A2 (68% identical), EIF4A1 (66% identical), DDX19A (36% identical), DDX19B (36% identical), DDX25 (34% identical), DDX3X (34% identical), DDX39B (33% identical), DDX3Y (33% identical), DDX17 (33% identical), DDX43 (32% identical), DDX39A (32% identical), DDX5 (32% identical), and 26 more.
Diseases named in the same sentence as EIF4A3 in open-access papers:
EIF4A3 is named in the same sentence as 66 diseases in open-access papers, as found by Europe PMC text mining. Sharing a sentence is not in itself a finding about the gene and the disease. The quoted sentences say what the papers report.
breast carcinoma (27 papers, 2020 to 2026). "The analysis also revealed that eIF4a3 levels were elevated in breast cancer compared to benign tissue and was associated with higher tumor stage at presentation ER+ tumors expressing homozygote SELENOP genotypes." (PMID 41563517, 2026). "The Clinicopathological associations of EIF4A3 were analyzed in our breast cancer specimens." (PMID 40092703, 2025). "In addition, the expression of cSERPINE2 in tumor tissues was positively related to the level of EIF4A3 in 27 clinical breast cancer specimens, suggesting that EIF4A3 was associated with cSERPINE2 expression." (PMID 36797769, 2023). "In addition, EIF4A3 promotes the formation of circSERPINE2 in breast cancer, which is shuttled to tumor-associated macrophages through exosomes and enhances the secretion of Interleukin-6, leading to increased proliferation and invasion of breast cancer cells." (PMID 39550559, 2024). "This study provides a theoretical basis for understanding the role of EIF4A3 in the malignant process of breast cancer." (PMID 40092703, 2025). "Taken together, our data suggested that the knockdown of EIF4A3 inhibits cell proliferation and promotes apoptosis in human breast cancer cells." (PMID 40092703, 2025). "In this study, we aimed to explore the specific molecular mechanism of EIF4A3 in promoting the malignant process of breast cancer in vivo and in vitro." (PMID 40092703, 2025). "The results showed that EIF4A3 was significantly upregulated in breast cancer and that high EIF4A3 expression correlated with poor prognosis in breast cancer patients." (PMID 40092703, 2025). "In conclusion, our findings demonstrated that knockdown of EIF4A3 inhibits breast cancer cell growth in vivo." (PMID 40092703, 2025). "In the present study, we mainly focused on exploring the role and detailed mechanism of EIF4A3 in the proliferation of human breast cancer cells." (PMID 40092703, 2025). "For example, EIF4A3 binds to circZFAND6 pre-mRNA and promotes circZFAND6 biogenesis in breast cancer." (PMID 39858034, 2025). "The results showed that EIF4A3 staining signals were much higher in breast cancer tissues than in adjacent tissues." (PMID 40092703, 2025). "In summary, our study showed that EIF4A3 was highly expressed in breast cancer, and depletion of EIF4A3 inhibited the proliferation of breast cancer cells both in vitro and in vivo." (PMID 40092703, 2025). "To investigate the role of EIF4A3 in the biological functions of breast cancer cells, we used two siRNAs to knock down the expression of EIF4A3 in MCF-7 and T47D cells." (PMID 40092703, 2025). "By contrast, hsa_circ_0068631 improves MYC mRNA stability by recruiting eukaryotic translation initiation factor 4A3 (EIF4A3) in breast cancer cells." (PMID 41318550, 2025). "These novel molecular probes present useful tools for further study of EIF4A3 in clinical treatment and make it possible for EIF4A3 to be a promising therapeutic target for breast cancer." (PMID 40092703, 2025). "We analyzed the correlation between EIF4A3 expression and the survival probability of breast cancer patients in the TCGA database to investigate the potential roles of EIF4A3 in breast cancer." (PMID 40092703, 2025). "We propose that as an effector of EIF4A3, CDC5L is regulated by EIF4A3 and that EIF4A3 can bind to its mRNA, which in turn affects the expression of downstream CyclinD1 and promotes the proliferation of breast cancer cells." (PMID 40092703, 2025). "In breast cancer, EIF4A3 promotes circIKBKB biogenesis, which activates NF-κB signaling to induce osteoclast differentiation and bone metastasis." (PMID 39550559, 2024). "We also tested the EIF4A3 expression among breast cancer cells and normal cells, the results showed that MDA-MB-231 and MCF-7 had higher EIF4A3 expression than MCF-10A, which was consistent with high expression of circ_0022382 in breast cancer cells." (PMID 39868374, 2024).
breast carcinoma (continued). "Blocking EIF4A3 pharmaceutically inhibits the circIKBKB biogenesis and bone-metastasis of breast cancer, which provides a novel therapeutic target for breast cancer treatment." (PMID 39550559, 2024). "For example, circ_0068631 recruited EIF4A3 to enhance c-Myc mRNA stability, which accelerated growth and metastasis of breast cancer." (PMID 37179359, 2023). "RNA pull-down and RNA immunoprecipitation (RIP) assays showed that hsa_circ_0068631 can bind to EIF4A3 and recruit EIF4A3 to increase c-Myc mRNA stability in breast cancer." (PMID 37296107, 2023). "Kaplan–Meier survival analyses indicated that higher EIF4A3 expression was associated with poor OS and RFS in the breast cancer Kaplan–Meier plotter database." (PMID 36797769, 2023). "Meanwhile, the selective EIF4A3 inhibitor eIF4A3-IN-2 decreased osteoblastogenesis and inhibited the bone metastasis induced by breast cancer cells." (PMID 37180585, 2023). "EIF4A3 is upregulated in various malignant tumours such as pancreatic cancer, breast cancer and cervical cancer." (PMID 35513835, 2022). "Previous studies have demonstrated that EIF4A3 is also highly expressed in many tumors, such as lung cancer, breast cancer, pancreatic cancer, colorectal cancer, and MM." (PMID 35637857, 2022). "Elevated levels of both SELENOF and eIF4a3 were observed in breast cancer tissues." (PMID 41563517, 2026). "In this paper, we explored the potential effects of EIF4A3 on cell proliferation in breast cancer." (PMID 40092703, 2025). "Our results showed that the expression of EIF4A3 was significantly upregulated in breast cancer, and overexpression of EIF4A3 could accelerate the growth of breast cancer cells." (PMID 40092703, 2025). "Subsequently, further experiments revealed that knockdown of EIF4A3 significantly suppressed the proliferation and colony formation of breast cancer cells both in vitro and in vivo, accompanied by elevated levels of p21 and p27 and reduced expression of CyclinD1 and Survivin." (PMID 40092703, 2025). "This suggests that EIF4A3 possesses tumor-promoting activity in breast cancer." (PMID 40092703, 2025). "In addition, EIF4A3 was found to bind to circZFAND6 pre-mRNA transcript upstream region, leading to the high expression of circZFAND6 in breast cancer." (PMID 38383334, 2024). "Moreover, hsa_circ_0068631 recruits EIF4A3, which increases expression of c-Myc in breast cancer, showing an important role in cancer metastasis." (PMID 38383334, 2024). "Furthermore, the expression of EIF4A3 was significantly increased in breast cancer tissues compared to normal tissues according to TCGA database analysis." (PMID 36797769, 2023). "The role of EIF4A3 has been described in some tumour pathologies such as glioblastoma multiforme or breast cancer, wherein EIF4A3 could facilitate circMMP9 and circSEPT9 cyclization, facilitating carcinogenesis." (PMID 36419260, 2022). "Importantly, treatment with inhibitor eIF4A3-IN-2 reduced circIKBKB expression and inhibited breast cancer bone metastasis effectively." (PMID 34325714, 2021). "In fact, EIF4A3 induced circMMP9 expression in glioblastoma and circSEPT9 in breast cancer cells." (PMID 33946584, 2021). "RNA-binding proteins such as AUF1 and EIF4A3 were reported to induce the production of circRNAs, in this study, we also demonstrated EIF4A3 could promote the production of circ_0022382 in breast cancer." (PMID 39868374, 2024). "Interestingly, protein abundance of HPRT1, HNRNPA0, IFIT3, CTNND1 and EIF4A3 predicted poor overall survival in breast cancer patients, however, PPM1A association was non-significant." (PMID 32532008, 2020). "METHODS: We utilized The Cancer Genome Atlas (TCGA) dataset to analyze the expressions of OTUB2, EIF4A3, and TPI1 in breast cancer tissues and specifically in triple-negative breast cancer (TNBC) tissues." (PMID 41857621, 2026).
breast carcinoma (continued). "Given the established ability of eiF4a3 to attenuate SELENOF translation, it was unexpected that both eIF4a3 and SELENOF levels were elevated in breast cancers." (PMID 41563517, 2026). "RESULTS: TCGA database indicated highly expressions of OTUB2, EIF4A3, and TPI1 in breast cancer tissues and TNBC tissues." (PMID 41857621, 2026). "CircNF1 is induced by eukaryotic initiation factor 4A-III (EIF4A3) in breast cancer and acts as a competitive endogenous RNA to activate the Rat sarcoma (RAS) pathway and facilitate the malignant progression of breast cancer." (PMID 40158127, 2025). "In this study, we explore the expression levels of SELENOF and eIF4a3, along with genotypes of SELENOF and the selenium transporter SELENOP, in breast cancer tissues from African American and Caucasian women using a tissue microarray (TMA) with relevant clinical data." (PMID 41563517, 2026). "Next, we collected 47 pairs of human breast cancer tissues and 60 nonpaired human breast cancer tissues to explore the expression of EIF4A3 by utilizing immunohistochemical staining." (PMID 40092703, 2025). "A study showed that circKIF4A could interact with EIF4A3 to stabilize SDC1 mRNA, which activates the c-src/FAK pathways and promotes breast cancer progression." (PMID 39858034, 2025). "However, the specific mechanism of the relationship between EIF4A3 and CDC5L in breast cancer is still unclear and requires further clarification." (PMID 40092703, 2025). "A TIMER2 analysis of EIF4A3 expression in tumors and normal tissues indicated that cancer expressed EIF4A3 notably more than normal tissues, such as BLCA, breast cancer, Cholangiocarcinoma, Colon adenocarcinoma, Esophageal carcinoma, etc. compared to the normal tissues." (PMID 37180585, 2023). "A strong negative correlation between T cell dysfunction and EIF4A3 expression was observed in breast cancer and melanoma, suggesting the potential of EIF4A3 as an immune regulator." (PMID 37777564, 2023). "The TIDE dataset showed a strong negative correlation between T cell dysfunction and EIF4A3 expression in breast cancer and melanoma." (PMID 37777564, 2023). "The RNA binding protein EIF4A3 is considered as an important regulator of post-transcriptional regulatory processes, and CCL2, as a powerful macrophage chemokine, was reported to be a target of STAT3 in breast cancer." (PMID 36797769, 2023). "However, EIF4A3 phosphorylation in other tumors, such as renal cancer and malignant hematological diseases, has not been investigated, while the signaling pathways in HCC, breast cancer, lung cancer, and other tumors are poorly understood." (PMID 34458150, 2021).
colorectal cancer (25 papers, 2016 to 2025). A primary or metastatic malignant neoplasm that affects the colon or rectum. "In addition, some researchers pointed out that H19 was associated with a poor prognosis in colorectal cancer, which promoted tumor growth by recruiting and binding to eIF4A3." (PMID 28658310, 2017). "Circ_0000467 was reported to be capable of binding eukaryotic translation initiation factor 4A3 (eIF4A3) in colorectal cancer cells to prevent nuclear translocation of eIF4A3." (PMID 39736850, 2025). "There have been further reports of this promoting effect of EIF4A3 on circRNAs biogenesis in other cancers, such as cervical cancer, hepatocellular carcinoma, and colorectal cancer." (PMID 37626035, 2023). "Although EIF4A3 has been reported to be closely related to tumorigenesis, such as tumorigenesis of colorectal cancer and pancreatic adenocarcinoma, its role in PCa has not yet been elucidated." (PMID 34696782, 2021). "For instance, lncRNA H19 demonstrates a poor prognosis of colorectal cancer and enhances tumor growth via recruiting eIF4A3." (PMID 32549791, 2020). "LncRNA H19 boosts tumor growth and predicts a poor prognosis in colorectal cancer through recruiting eIF4A3." (PMID 32549791, 2020). "To further test the UPF1 and EJC dependence of proximal 3′UI-containing NMD targets in human cells, we knocked down UPF1 or EIF4A3 in a human colorectal carcinoma cell line (HCT116), and assessed levels of a subset of 3′UI-containing transcripts." (PMID 32502192, 2020). "Circ-SIRT1 promotes colorectal cancer cell proliferation by recruiting and binding eIF4A3." (PMID 41002382, 2025). "Another study on colorectal cancer showed that the exosome circCOL1A1 derived from cancer cells could also promote angiogenesis by recruiting the EIF4A3 protein and activating the Smad2/3 signaling pathway." (PMID 41584514, 2025). "Moreover, EIF4A3-induced circ_0084615 promoted colorectal cancer proliferation, migration, and invasion via the miR-599/ONECUT2 axis." (PMID 37322413, 2023). "It was also reported that circ-SIRT1 binds to the eukaryotic translation initiation factor 4A3 (EIF4A3) in colorectal cancer cell lines, preventing its inhibitory impact on epithelial–mesenchymal transition and encouraging the proliferation and invasion of colorectal cancer cell lines." (PMID 38003674, 2023). "The alteration on these modifications impacts on the stability and translation of downstream targets of ZFAS1 (such as EIF4A3 and LAMC2), which directly impacts the development of colorectal carcinoma (CRC)." (PMID 38406265, 2024).